LEP (leptin)
Diseases named in the same sentence as LEP in open-access papers (continued):
Sharing a sentence is not in itself a finding about the gene and the disease.
dementia (51 papers, 2010 to 2026). Loss of intellectual abilities interfering with an individual's social and occupational functions. "Leptin inhibits the expression of BACE, the gene encoding a secretase that cleaves the Aβ precursor, whereas leptin contributes to the reduction of tau phosphorylation, neurogenesis, synaptogenesis, and risks of developing dementia." (PMID 40420360, 2025). "This biphasic pattern mirrors leptin’s relationship to dementia risk: protective in midlife, but often reversed or normal in late life." (PMID 41516046, 2025). "Among females with BMI < 25 kg/m2, each 1-SD increase in log leptin (0.91 ng/mL) was associated with 32% reduction odds of dementia or MCI." (PMID 41516046, 2025). "Path analysis was employed to explore how leptin relates to the association between adipose-related metabolic dysfunction and dementia through inflammatory pathways in patients with AD pathology (n = 15)." (PMID 40521397, 2025). "Elevated leptin levels can control hippocampal synaptic plasticity and processing of amyloid beta, leading to a reduced dementia risk." (PMID 39010668, 2024). "One study found a greater association between higher serum leptin levels and a lower frequency of dementia in women with normal BMI’s as compared to obese women." (PMID 35739488, 2022). "Higher circulating levels of leptin have been associated with a reduced incidence of dementia and AD and with higher brain volume." (PMID 34237705, 2021). "Studies in humans have shown that high leptin levels are negatively correlated with late-in-life dementia risk." (PMID 31178685, 2019). "Data from Lieb and colleagues found that higher levels of leptin were associated with higher total cerebral volume and lower temporal horn volume measured with volumetric brain MRI in dementia-free individuals than AD." (PMID 29867443, 2018). "In a prospective study of the Framingham original cohort, circulating leptin levels were associated with reduced incidence of dementia and AD in asymptomatic older adults." (PMID 29156608, 2017). "have reported that in normal individuals, elevated plasma leptin levels are associated with lower incidence of dementia, AD and larger brain volumes." (PMID 25453257, 2015). "Controvertibly, dementia and AD development in older adults has been linked to low plasma leptin levels." (PMID 25251414, 2014). "Recent works have indentified leptin levels as good indicators of susceptibility to prevent AD in elderly population: higher plasma concentrations of leptin correlated with a significantly lower risk of dementia and AD." (PMID 22848520, 2012). "Increased plasma leptin levels have been found to be associated with a lower risk ofincident dementia and Alzheimer's disease (AD)." (PMID 21633502, 2011). "In multivariate models, higher leptin levels were associated with a lower risk of dementia and AD (hazard ratio per 1-SD increase in log leptin was 0.68 [95% CI, 0.54–0.87] for all-cause dementia and 0.60 [95% CI, 0.46–0.79] for AD)." (PMID 21070531, 2010). "Cross-sectional MRIs on 198 dementia-free participants of the Framingham cohort revealed that plasma leptin was associated with greater total cerebral brain volume and lower lateral ventricular volume following adjustment for age, sex, education, vascular risk factors, and BMI." (PMID 41516046, 2025). "GLP-1RAs may therefore reduce leptin levels and leptin resistance, potentially contributing to the observed reduction in dementia risk." (PMID 41516046, 2025). "For example, higher levels of leptin were associated with a lower risk of dementia." (PMID 30368247, 2018). "In the case of leptin, as compared to adiponectin, the opposite direction of correlations with the same parameters were stated in all-cause dementia i.e. positive correlation with BMI, fasting glucose, insulin, HOMA-IR, IL-6 and hsCRP and positive correlation with HDL-C." (PMID 28421328, 2017).
dementia (continued). "Thus studies of the individuals that form the Framingham cohort have revealed that decreased circulating leptin levels are predictive of an increased risk of developing dementia or AD." (PMID 22013440, 2011). "Besides further confirming the correlation between leptin levels and brain size, a prospective study of 785 healthy persons from the Framingham cohort showed that higher leptin levels were associated with a lower risk of dementia and AD in lean, leptin-sensitive people." (PMID 26881138, 2016). "This study employed path analysis to investigate the role of leptin in linking adiposity to dementia through inflammatory pathways in the AD continuum." (PMID 40521397, 2025). "In the Texas Alzheimer’s Research and Care Consortium (TARCC) study, eight adipokines, including leptin, were analyzed as a combined “adipokine” construct using structural equation modeling to examine their relationship with dementia severity." (PMID 41516046, 2025). "So, before addressing the connection between leptin and dementia, it is important to analyse the relationship and implication of leptin with these different aspects of cognition." (PMID 35563589, 2022). "In contrast, other studies have shown a larger frequency of dementia among people with higher leptin concentration." (PMID 30893833, 2019). "For these reasons, the elevation of leptin has been suggested as a therapeutic alternative for dementia." (PMID 31178685, 2019). "In the whole dementia group the mean levels of adiponectin (p = 0.002) and resistin (p = 0.00009) were significantly higher and leptin/adiponectin (L/A) ratio (p = 0.015) was significantly lower as compared to the control group." (PMID 28421328, 2017). "This is congruent with the low BMI and low leptin levels observed cross-sectionally in those with dementia, and that cognition is enhanced with the amylin analog, pramlintide." (PMID 28690913, 2017). "Recently, circulating leptin has been described to beassociated with reduced incidence of dementia and AD and with a higher totalcerebral brain volume determined by magnetic resonance imaging in asymptomatic olderadults." (PMID 21633502, 2011). "•Used path analysis to explore leptin's role linking adiposity and dementia." (PMID 40521397, 2025). "In a prospective study of 785 people without dementia, higher leptin was linked to a lower risk of incident dementia and AD." (PMID 39822062, 2025). "Increased levels of leptin have been associated with reduced dementia incidence in non-obese adults and larger brain volume." (PMID 41403901, 2025). "This study included participants with different types of dementia, and they were compared with controls with normal cognitive function.Adiponectin, leptin, resistin, pro-inflammatory markers, vitamin D, cholesterol, and markers of glucose metabolism were assessed." (PMID 37363537, 2023). "Some researchers have proposed that Leptin, an adipokine, may be a better predictor of dementia/mild cognitive impairment than standard anthropometric measures." (PMID 35739488, 2022). "Thus, adipokines, secreted by adipose tissue, communicate with the CNS, playing a role in the progression of AD and other dementias; among them, leptin has neuroprotective effects at the level of CNS." (PMID 35563589, 2022). "Interestingly, leptin plays an important role in the pathogenesis of human dementia, and has been tested as therapy." (PMID 31130848, 2019). "Leptin has been demonstrated to have a neuroprotective role against AD pathology and dementia." (PMID 28421328, 2017). "The lack of association between leptin and risk of dementia was not seen in obese individuals, possibly due to leptin resistance." (PMID 26881138, 2016). "A body of evidence suggests that leptin, and other adipocytokines might be involved in pathogenesis of deterioration of cognition and dementia." (PMID 26432692, 2016). "Some studies suggest that adipokines, and principally leptin, may influence the pathogenesis of dementia." (PMID 22927962, 2012).
dementia (continued). "Because these dMRI metrics are among key biomarkers designed to reflect brain WM neurodegeneration, serum leptin can be used as a more readily available biomarker prior to using these more elaborate methods to screen for brain WM changes related to AD and related dementias." (PMID 39822062, 2025). "However, it remains unclear whether and how leptin contributes to the link between adiposity and dementia through the induction of inflammation." (PMID 40521397, 2025). "However, it remains unclear whether and how leptin contributes to the link between adipose tissue dysfunction and dementia." (PMID 40521397, 2025). "In particular, as diet plays a role in the onset of dementia—even if not completely understood at present—it is noticeable that other dietary metabolites, including the serum uric acid, show a U-shaped relationship with cognition that is very similar to the one we found here with leptin." (PMID 30893833, 2019). "Across all participants, plasma leptin was positively correlated with MMSE scores and negatively with clinical dementia rating (CDR) scores." (PMID 41516046, 2025). "On univariate analyses these included age, sex, CAD, dementia, ASA ≥ 3, smoking, eGFR, haemoglobin, 25(OH)D, PTH, leptin, adiponectin and resistin levels, but with different impact on specific outcomes by HF type." (PMID 22333003, 2012). "Examination of the highlighted keywords revealed the commonality between HF and dementia, namely IL6, ACE, APOE, APP, ADIPOQ, LEP, and NPPB, suggesting that these proteins may link the two pathologies." (PMID 40699836, 2025). "As expected, the significant negative correlation between leptin and adiponectin was stated in dementia (R = −0.327, p = 0.000002; data not shown)." (PMID 28421328, 2017). "In the present study, in opposition to leptin and adiponectin (both in dementia and non-demented elderly controls) we did not observe any correlation between resistin and metabolic parameters i.e. BMI, fasting glucose, insulin and HOMA-IR index." (PMID 28421328, 2017). "In accordance with previous studies showing that blood leptin levels are not different between individuals with and without dementia, our findings suggest that blood leptin, as well as adiponectin, does not seem to sensitively reflect the current disease state." (PMID 36329496, 2022). "Moreover, we did not observe any correlation between resistin and adiponectin and leptin, both in whole dementia and control group (data not shown)." (PMID 28421328, 2017). "Moreover, both in all dementia patients and non-demented elderly controls, we confirmed a high positive correlation between leptin and selected metabolic parameters i.e. BMI, fasting glucose, insulin and HOMA-IR index previously stated in elderly subjects." (PMID 28421328, 2017). "Similarly, midlife leptin was not related to dementia over 32 years, suggesting that alterations in circulating leptin levels associated with AD may emerge in late life but not during midlife." (PMID 41516046, 2025).
systemic lupus erythematosus (50 papers, 2010 to 2025). An autoimmune multi-organ disease typically associated with vasculopathy and autoantibody production. "It's interesting to observe that in lupus models, autoantibody synthesis and immunological imbalance are tightly linked to abnormal leptin expression." (PMID 41476956, 2025). "Recent studies have analyzed the association of leptin-related polymorphisms in patients with lupus to decipher its possible impact on susceptibility to the disease." (PMID 35967162, 2022). "In a mouse model of leptin-deficient lupus, Tregs were increased until supplemental leptin decreased them." (PMID 33557015, 2021). "B cells express LEPRb on the cell surface, leptin signalling in leptin deficient mice (ob/ob) showed that these animals are protected against lupus development after pristane injection." (PMID 33673730, 2021). "Leptin-deficient lupus mice exhibited decreased TH17 cells, anti-DNA antibody titers, and ameliorated nephritis." (PMID 33557015, 2021). "In SLE, the disease-associated higher leptin serum levels were negatively correlated with disease severity and number of Treg cells, and fasting-induced hypoleptinaemia was related to Treg population recovery in lupus-prone mice." (PMID 29910742, 2018). "Leptin concentrations also associated with cardiovascular risk in patients with lupus." (PMID 24286214, 2013). "Epidemiological studies have shown that the levels of serum adipokine such as leptin and resistin are associated with the risk of developing systemic lupus erythematosus (SLE)." (PMID 38805491, 2024). "It have been revealed that leptin plays a crucial role in the susceptibility to multiple sclerosis (MS) and systemic lupus erythematosus (SLE)." (PMID 33083462, 2020). "Elevated serum resistin levels have been observed in patients with dermatomyositis/polymyositis, systemic lupus erythematosus, and vasculitis syndrome, and leptin was higher in adults with RA and juvenile dermatomyositis compared to healthy controls." (PMID 40085146, 2025). "While mRNA expression of pro-inflammatory leptin in PVAT was similar in lupus mice versus control mice, plasma leptin levels were decreased in lupus mice." (PMID 37006244, 2023). "In murine lupus induced by pristane and New Zealand Black (NZB) × New Zealand White (NZW)F1 (NZB/W) mouse model of spontaneous SLE, leptin deficiency protects from the development of autoantibodies and renal disease." (PMID 37006245, 2023). "In mouse models of lupus, it has been shown that leptin promotes spontaneous lupus and that its antagonism decreases disease manifestations and aids in immune regulation." (PMID 35967162, 2022). "Recently, a possible role of leptin in systemic lupus erythematosus (SLE) pathogenesis has been emphasized." (PMID 33008429, 2020). "Leptin also promoted phagocytosis of apoptotic cells by macrophages in lupus-prone mice, which increase the availability of apoptotic-derived antigens to T cells and subsequent development of self-antigen-reactive T cells." (PMID 29910742, 2018). "At cellular level, leptin promoted Th1 responses in human CD4+ T cells and in lupus-prone mice via RORγ transcription, whereas leptin neutralization inhibited Th17 responses in autoimmune-prone mice." (PMID 29910742, 2018). "Leptin promoted T cell survival and proliferation of autoreactive T cells in mice with an autoreactive T cell repertoire, including (NZBxNZW)F1 lupus-prone mice." (PMID 29910742, 2018). "In mice prone to lupus development, leptin increases macrophages phagocytosis of apoptotic cells by increasing cAMP levels, favoring the availability of self-antigen from apoptotic cells." (PMID 25918733, 2015). "Systemic lupus erythematosus patients had higher leptin levels, and there was a significant correlation between leptin level and Lp(a)." (PMID 23304154, 2012). "Enhanced leptin levels could be a factor triggering autoreactive T‐lymphocytes and expansion of Th17 cells in lupus‐prone mice." (PMID 37275420, 2023).
systemic lupus erythematosus (continued). "Similarly, an increased circulating leptin and decreased adiponectin can influence systemic lupus erythematosus (SLE) severity." (PMID 37275420, 2023). "Further research is needed to explore the connection between leptin and lupus, to clarify its role in the development of the disease, and whether it can be used as a tool to aid early diagnosis." (PMID 35967162, 2022). "The keywords used included leptin, leptin receptor, level, systemic lupus erythematosus, and SLE." (PMID 35967162, 2022). "However, in the LEP gene, they showed that lupus patients with pericarditis had higher frequencies of the TT genotype and T allele frequencies of the rs2071045 polymorphism." (PMID 35967162, 2022). "Moreover,leptin treatment further enhanced endothelial dysfunction and atheroscleroticlesions in lupus-prone mice fed a high fat diet." (PMID 35842184, 2022). "Experiments using mouse models showed that in lupus-like induced diseases mediated by pristane injection, high leptin levels have an increased response of pristane generated IgG secretion and accelerate lupus in NZB/W mice or MRL/Mp-Faslpr mice, which develop SLE spontaneously." (PMID 33673730, 2021). "Moreover, leptin promoted the phagocytosis of apoptotic cells by macrophages from lupus mice, via modulation of cAMP levels." (PMID 29910742, 2018). "High leptin secretion has been reported in lupus patients, and thus, this secretion may be one of the key reasons underlying the induction of mTORC1-meditated inhibition of Treg cell differentiation, as well as proinflammatory Th17 cell and other effector T cell expansion in SLE." (PMID 27597882, 2016). "Therefore, by the mechanisms described, leptin may be involved in the pathogenesis of lupus." (PMID 35967162, 2022). "Leptin has also been reported to induce retinoic acid receptor-related orphan receptor gamma-t (RORγt) expression and expand TH17 cells in lupus-prone mice." (PMID 33557015, 2021). "In systemic lupus erythematosus (SLE), leptin levels have been reported to be elevated in human patients and correlate with severity in a mouse model of the disease." (PMID 29868016, 2018). "Leptin promotes Th17 responses in normal human CD4+ T cells and in (NZB × NZW) F1 lupus-prone mice, by inducing RORγ transcription, whereas, on the contrary, its neutralization in those autoimmune-prone mice inhibits Th17 responses." (PMID 24778633, 2014). "Systemic lupus erythematosus (SLE) is a chronic autoimmune disorder that is characterized by B- and T-lymphocyte dysfunction and altered cytokine production, including elevated levels of the adipocytokine leptin." (PMID 38031726, 2023). "Based on the findings of this review, leptin levels do not appear to correlate with disease activity in lupus patients." (PMID 35967162, 2022). "Comparison of clinical characteristics, leptin, and adiponectin levels between patients with systemic lupus erythematosus (SLE) with proteinuria vs. those without lupus nephritis (LN)." (PMID 28898254, 2017). "However, lupus can be extremely complex and exhibit high clinical heterogeneity, which was not fully demonstrated in the leptin-overexpressing mice." (PMID 30169503, 2018). "Thus, Hahn and colleagues found that leptin administration enhanced pro-inflammatory high density lipoprotein scores as well as atherosclerosis in lupus prone but not non-immune mice." (PMID 24286214, 2013).